FTO (FTO alpha-ketoglutarate dependent dioxygenase)
Diseases named in the same sentence as FTO in open-access papers (continued):
Sharing a sentence is not in itself a finding about the gene and the disease.
Obesity (continued). "The FTO gene has been identified as a potential risk factor for the etiology of obesity." (PMID 36278751, 2022). "FTO rs9939609 is an established obesity risk factor and is the most widely studied SNP of this gene, but other FTO polymorphisms may also contribute to BMI or rCBF independently or in combination with FTO rs9939609." (PMID 36072887, 2022). "Alteration of the kynurenine pathway may be one of the mechanisms underlying the action of FTO in the pathogenesis of obesity and its related effects." (PMID 35757166, 2022). "Stratification analysis of ethnicity revealed that the augmented risk of OA due to FTO polymorphism may exert its effect through obesity in the Caucasian population." (PMID 36213660, 2022). "Iroquois-related homeobox 3 is considered to be a determinant for obesity, in relation to the fat mass and obesity associated (FTO) genes, due to the role of Irx3 in neurogenesis at the paraventricular nucleus of the hypothalamus, developed from the anterior hypothalamus." (PMID 35546872, 2022). "Furthermore, different common FTO SNPs show variable association with obesity in different populations, thus challenging the inclusion of obesity risk estimates in other world populations." (PMID 36235854, 2022). "Finally, it is concluded that FTO genotype has a long-term effect on MetS or obesity susceptible patients." (PMID 35528183, 2022). "Furthermore, obesity is also correlated with the development of MS due to the polymorphisms found in fat mass obesity (FTO)-related genes." (PMID 35806081, 2022). "The FTO rs1421085 (C > T) variant led to higher macronutrient intake, obesity, and T2DM." (PMID 36536469, 2022). "In this study, we also investigated the influence of two representative obesity-associated genes (FTO and MC4R) on body composition, metabolic parameters, and nutrient intake, as well as changes in these factors after intervention within the MeDiet group and control group." (PMID 35845810, 2022). "Although polymorphisms within the intron 1 of the FTO gene were first reported to be associated with obesity, the physiological role of the FTO gene remains unclear." (PMID 36163017, 2022). "Dr. Carnell then described the biobehavioral susceptibility model of obesity, which proposes that genes (e.g., FTO, fat mass and obesity-associated) and family environment interact to influence appetitive traits, including the responsivity to food cues in the wider environment." (PMID 34934178, 2022). "Our findings replicate and verify the association between FTO SNPs and elevated risk of obesity." (PMID 36235854, 2022). "The strong association between FTO SNPs or overweight/obesity with an increased risk of cancers suggests that the obesity‐associated function of FTO in metabolism may also contribute to its effects in cancers." (PMID 36403211, 2022). "Furthermore, the fat mass and obesity-associated gene (FTO) of the hippocampus and hypothalamus were down-regulated in the exercise group (p < 0.001)." (PMID 36163017, 2022). "Likewise, a previous study reported that inactivation of the FTO gene in mice fed an HFD provoked a reduction in fat mass linked to obesity." (PMID 35800074, 2022). "Interestingly, variants in the FTO gene, e.g., rs9939609 and rs1421085, were also reported to be associated with IR and obesity." (PMID 35692393, 2022). "FTO rs9939609 polymorphism was significantly associated with an increased risk of obesity." (PMID 36499740, 2022). "The researchers attributed the sex-specific effect to the differences in fat distribution and/or physical activity between men and women, which might influence the effects of FTO variants on obesity/adiposity." (PMID 35721732, 2022). "In addition to this, six SNPs of the FTO gene (rs6499640, rs1421085, rs8050136, rs3751812, rs9939609, and rs9930506) were mostly associated with obesity." (PMID 35923209, 2022). "Recently, a gender-specific association of FTO gene polymorphism with risk of obesity was revealed." (PMID 35207726, 2022).
Obesity (continued). "The Fat mass and obesity-associated gene, also known as FTO (alpha-ketoglutarate-dependent dioxygenase), was the first obesity susceptibility gene identified through Genome-Wide Association Studies (GWAS) and remains the locus with the greatest effect on adiposity in different human populations." (PMID 34990463, 2022). "It is unclear whether the association between the FTO genotype and lysophosphatidylcholine was the result of the association of FTO with obesity." (PMID 35757166, 2022). "FTO is widely known to be associated with obesity from previous reports on different ethnic groups, and it has been strongly associated with several adiposity phenotypes, such as extreme obesity, early-onset obesity, the BMI, BF%, WC, and the WHR." (PMID 35051171, 2022). "However, in the Asian population, the relationship between FTO gene polymorphism and obesity remained ambiguous." (PMID 36213660, 2022). "The genetic risk scores calculated for T2D in indigenous are high and similar to those calculated for Americans and East Asians, while the estimates obtained for obesity are low, probably due to the low frequencies of the risk allele of the FTO gene found in our samples." (PMID 35560161, 2022). "Fat mass and obesity-associated protein (FTO) is a member of the Fe (II)- and oxoglutarate-dependent AlkB dioxygenase family, and is known for the strong association of the multiple single-nucleotide polymorphisms located in its intron 1 with risk of obesity." (PMID 35769384, 2022). "Moreover, in European adolescents with obesity the homozygosity for the rs9939609 FTO SNP was critically associated with trunk-weighted." (PMID 36452324, 2022). "Studies have also shown that FTO variants affect the morbidity of obesity." (PMID 36536469, 2022). "The genetic risk scores calculated for diabetes in indigenous people are high and similar to those calculated for Americans and East Asians, while the risk scores for obesity are low, probably due to the low frequencies of the risk allele studied in the FTO gene." (PMID 35560161, 2022). "While FTO gene polymorphisms associated with obesity have substantial variability in allele frequencies among ethnoterritorial groups, comparable allele recording frequencies of multiple SNPs across representatives of the same ethnoterritorial group also exist." (PMID 36362270, 2022). "FTO has been correlated with obesity in humans based on genome-wide association studies since 2007." (PMID 35422475, 2022). "Herein, we found that FTO was the only gene associated with two different traits: obesity [48••, 49] and blood pressure, and interacting with four different environmental factors: physical activity [48••, 49], smoking habit [48••], sweet beverage [48••] and alcohol consumption." (PMID 35948824, 2022). "We analyzed twenty-one FTO SNPs with previously reported association to obesity." (PMID 36235854, 2022). "FTO was the first gene having the strongest genetic association with polygenic obesity." (PMID 35409166, 2022). "Furthermore, genome-wide association studies have revealed that the FTO gene region is linked to obesity-related traits such as BMI value, hip circumference, and body weight." (PMID 35806402, 2022). "In 2011, studies reported that FTO controls the dopaminergic circuit in the brain, which has been shown to be associated with drug and alcohol abuse, as well as with the urge to overeat in people with higher levels of BMI and obesity." (PMID 35528183, 2022). "For instance, C/EBPα could induce PPARγ expression by identifying the C/EBP effector domain of the PPARγ promoter, and C/EBPα may act as a positive regulator binding to fat mass and obesity associated gene (FTO) promoter and activates the gene transcription." (PMID 33502338, 2021).
Obesity (continued). "Given that FTO polymorphism is associated with various human metabolic diseases, including obesity, diabetes, and cardiovascular disease, it will be interesting to study how FTO and NADPH-dependent m6A demethylation contributes to metabolic processes in normal and pathological conditions." (PMID 33573224, 2021). "Our research included older children (6.6–17.7, median 14.6), which may suggest that the impact of the FTO gene on the risk of obesity increases with age." (PMID 34063412, 2021). "The findings from the present study provide no consistent statistically significant evidence for an association of the five investigated obesity-associated genes (FTO, TMEM18, MC4R, SEC16B, and BDNF) with baseline anthropometric traits or their changes after 12 months of behavioural intervention." (PMID 33801339, 2021). "Furthermore, we demonstrated that fat mass and obesity-associated (FTO)-dependent N6-methyladenosine (m6A) demethylation was responsible for the upregulation of AC008 in OA." (PMID 34737423, 2021). "Most associated genes that are reported to be associated with obesity are – FTO rs9939609 and MC4R rs17782313, recent studies also reported ACE I/D rs4646994 and MTHFR C677T rs1801133 gene polymorphisms to be associated with obesity specifically in Indian population." (PMID 34414818, 2021). "FTO has been reported to be associated with obesity and diabetes." (PMID 34503454, 2021). "FTO is one of the leading genes associated with obesity and BMI42,43." (PMID 34521966, 2021). "The purpose of this study is to evaluate whether daily fiber intake can modify the association between genetic variations of the FTO gene and obesity in the Polish Caucasian population." (PMID 34829664, 2021). "Therefore, the aim of this study is to shed light on the effects of two genes, previously reported to be associated with obesity (FTO and FGF21), on dietary patterns." (PMID 34095191, 2021). "RIF is associated with the downregulation of the FTO gene expression in subjects with obesity, and this may explain, at least in part, its favorable metabolic effects." (PMID 35372458, 2021). "Genome-wide association studies have identified FTO as an obesity-associated gene." (PMID 34393992, 2021). "For instance, the FTO gene, which has been shown to be associated with obesity and atypical depression, might also have an impact on dietary choices during depressive episodes." (PMID 33653007, 2021). "Moreover, diet-induced inflammation is significantly associated with the risk of overweight adults with the rs9939609 polymorphism of the Fat Mass and Obesity Associated (FTO) gene." (PMID 34869441, 2021). "Therefore, the current work was designed to find out how the observance of RIF by fasting people with obesity will be associated with changes in the genetic expression of FTO." (PMID 35372458, 2021). "Interestingly, recently, the successful introduction of FTO, one specific Homo sapiens gene associated with obesity and fat mass, into rice and potato largely increased the productivity and biomass." (PMID 34885674, 2021). "High AMD1 level could promote SRY‐box transcription factor 2 (SOX2), Kruppel like factor 4 (KLF4), and NANOG expression of HCC cells through obesity–associated protein (FTO)‐mediated mRNA demethylation." (PMID 33783988, 2021). "Furthermore, the identification of fat mass and obesity-associated (FTO) gene, encoding the first RNA demethylase discovered, indicates that RNA modification can be an epigenetic marker." (PMID 34199279, 2021). "However, it has been reported that FTO genotype had a strong association with obesity via altering the IRX3 gene expression level." (PMID 34399781, 2021). "In another view, individuals who have mutant allele of both genes may be neutral towards obesity, because the positive effect of the FTO rs9939609 gene polymorphism is reduced by the MC4R rs17782313." (PMID 34414818, 2021).
Obesity (continued). "Concurrent associations between FTO variants, obesity, and dietary intake have been noted in several ethnic groups, including our previous report that FTO rs9939609 TT genotype was associated with obesity and preference for a high-fat diet in adult individuals from Jakarta." (PMID 34743743, 2021). "Gene variants of the FTO gene have been associated with increased obesity in the past." (PMID 34366884, 2021). "Another study conducted on the Polish population investigated whether the FTO A/T polymorphism influenced the effects of exercise training and obesity-related traits." (PMID 34064570, 2021). "Therefore, it is reasonable to expect that if FTO variants have a genetic association with obesity, they are also likely to have a close genetic association with CRC." (PMID 34650918, 2021). "Interestingly, the fat mass and obesity‐associated (FTO) gene, which is a well‐known marker for obesity, is increased by CJPE treatment." (PMID 33410284, 2021). "Moreover, multiple other types of molecules with various biological functions, such as fat mass and obesity-associated (FTO), have been studied and demonstrated to bring about functional consequences of AS in adipogenic regulators." (PMID 33795017, 2021). "In addition, studies have reported that dysregulation of FTO is also associated with obesity, growth retardation and other diseases." (PMID 34794452, 2021). "However, it has been postulated that associations of some FTO variants with obesity can occur due to their influence on dietary intake." (PMID 34829664, 2021). "However, evidence shows that performing physical activity can significantly attenuate the rs9939609 SNP of the FTO gene and other genes associated with obesity and metabolic alterations." (PMID 34208143, 2021). "Among these regions, FTO was strongly associated with obesity and BMI22." (PMID 34521966, 2021). "In addition, some studies found that the association between FTO gene and obesity is mediated by another genes." (PMID 34399781, 2021). "The aim of this study was to explore the potential effect of fat mass and obesity-associated (FTO) rs3751812, rs8050136, rs9939609, rs6499640, rs8044769, and rs7190492 genotypes and dietary fiber intake on the obesity-related parameters and lipid profile in the Polish population." (PMID 34829664, 2021). "Vitamin D level was reported to be inversely related to obesity, and FTO gene may affect the association between vitamin D and obesity." (PMID 34490746, 2021). "FTO, one of the m6A demethylases, links to a predisposition to obesity in children and adults." (PMID 34794452, 2021). "For example, the adrenergic receptor beta-2 (ADRB2), adrenergic receptor beta-3 (ADRB3), guanine nucleotide-binding protein (GNB3), uncoupling protein 1 (UCP1), and fat mass- and obesity-associated (FTO) genes are all reported to have associations with obesity." (PMID 34055005, 2021). "We compared methylation profiles in sperm quantified by bisulfite pyrosequencing, at promoter-associated CpG sites of genes involved in metabolism including fat mass and obesity-associated (FTO) and melanocortin-4 receptor (MC4R) from six vegans and 34 omnivores." (PMID 33767672, 2021). "Interestingly, genetic variants within the FTO gene are strongly associated with obesity and robustly replicated in many studies." (PMID 34950106, 2021). "Rhein has been identified to inhibit fat mass and obesity-associated (FTO) demethylase activity." (PMID 34790688, 2021). "FTO is known to be tightly associated with increased body mass and obesity in humans 103-105." (PMID 33390849, 2021). "FTO genetic variants with obesity can differ by ethnicity and dietary preference." (PMID 34743743, 2021). "In addition, FTO overexpression leads to obesity and increased appetite, while loss protein evolves in lean phenotypes." (PMID 33743080, 2021). "FTO andMC4R were reported to be associated with obesity in PCOS patients." (PMID 35655906, 2021).
Obesity (continued). "FTO was initially identified to be associated with obesity and type II diabetes." (PMID 34737423, 2021). "Glucocorticoid receptor (GR) mediated corticosterone-induced fatty liver syndrome (FLS) in the chicken by transactivation of Fat mass and obesity associated gene (FTO), leading to demethylation of N6-methyladenosine (m6A) and post-transcriptional activation of lipogenic genes." (PMID 34872591, 2021). "One study found that reduced outdoor activities may increase the risk of obesity in people carrying FTO rs9939609-A among Kazakh school-aged children." (PMID 33668547, 2021). "Newly published studies showed that diets might modify the effect of the FTO variant on obesity, but these data are conflicting and are limited by a small sample size." (PMID 34829664, 2021). "A meta-analysis suggests that FTO may represent a low-penetrance susceptible gene for obesity that may vary according to ethnic composition of the population." (PMID 33729310, 2021). "Interestingly, variants in the FTO gene correlated to a decrease in the presence of obesity, which is a risk factor for retinopathy." (PMID 34442333, 2021). "Interestingly, Speakman indicated that FTO gene polymorphisms mediate their obesity effects via nearby genes such as RPGRIP1L and IRX3." (PMID 34399781, 2021). "CUX1 and its related pathways such as the AMPK pathway could therefore be an important target of breastfeeding and might potentially play a role in modulating the risk of obesity in individuals carrying variants in the FTO gene." (PMID 34937578, 2021). "In addition, it has recently been found that adapting the intake of different macronutrients to the other genotypes linked to several FTO gene polymorphisms (rs9939609, among them) modifies the risk of obesity and metabolic disorders." (PMID 34208143, 2021). "Additionally, most obesity-related polymorphisms of the FTO gene are intronic and in strong linkage disequilibrium; for this reason, it has not yet been possible to determine SNPs affecting gene expression." (PMID 34345232, 2021). "Fat mass and the obesity-associated gene (FTO) may increase the risk of metabolic syndrome in subjects." (PMID 34684698, 2021). "Among all of these, FTO (Fat mass and obesity-associated) gene with a high rate of genetic variations may has a key role in life-long obesity." (PMID 34399781, 2021). "RIF is linked to the downregulation of FTO gene expression in subjects with obesity, which might explain, at least in part, its beneficial metabolic benefits." (PMID 35372458, 2021). "The Iroquois homeobox 3 (IRX3) gene was recently reported to be a functional downstream target of a common polymorphism in the FTO gene, which encodes an obesity-associated protein; however, the role of IRX3 in energy expenditure remains unclear." (PMID 33776928, 2021). "Thus, the FTO variants are either directly or indirectly responsible for the progressionof PCOS in addition to their previously known role in obesity." (PMID 35655906, 2021). "Furthermore, in carriers of the FTO obesity risk allele, lipolysis of fat cell is decreased, highlighting the possible role of FTO gene in fat metabolism." (PMID 34399781, 2021). "In 2007, three independent studies showed that a cluster of single nucleotide polymorphisms (SNPs) in the first intron of the fat mass and obesity-associated gene (FTO) is strongly associated with body mass-related traits and predisposes to overweight and obesity among children and adults." (PMID 34064570, 2021). "Besides their developmental functions, IRX3 and IRX5 have been highlighted as determinants of human obesity in connection with the intronic obesity risk variants of FTO, a gene in the vicinity of the IRXB cluster." (PMID 34795556, 2021). "Meta-analysis has demonstrated the associations between FTO SNPs and obesity risk." (PMID 34675880, 2021).